IL18 (interleukin 18)
Diseases named in the same sentence as IL18 in open-access papers (continued):
Sharing a sentence is not in itself a finding about the gene and the disease.
tumor (continued). "IL18 stained cells were scattered through tumor stroma and adjacent to the tumor edge." (PMID 31923221, 2020). "Furthermore, in multivariate Cox regression, downregulation of NLRP6 and IL-18 in the epithelium was associated with a worse outcome, after adjustment on TNM tumor stage (NLRP6: OR 3.25 [95CI: 1.27–8.28], p = 0.013; IL-18: OR 2.6 [95CI: 1.02–6.63], p = 0.045)." (PMID 33255437, 2020). "Like IL-18, IL-33 was shown to have pro- and anti-tumor effects." (PMID 33261061, 2020). "For instance, IL-33 release in murine HCC showed to markedly inhibit tumor growth via activated CD4+ and CD8+ T cells, in IL-33-expressing tumor-bearing mice, while IL-18/IL-12 cytokine therapy was effective in tumor regression prompted by induction of NK cells." (PMID 32899197, 2020). "To reveal whether the senescence induction in tumor cells is dependent on IFN-γ/TNF-α produced by IL-2/IL-12/IL-18-stimulated γδ T cells, we neutralized IFN-γ/TNF-α by anti-IFN-γ antibody or anti-TNF-α antibody or both antibodies." (PMID 31947966, 2020). "High levels of cytokines, especially IL-1β and IL-18, were detected in the tumor microenvironment." (PMID 33015196, 2020). "Consequently, the authors designed DR-18, an IL-18 resistant to IL-18BP inhibition, which enhances tumor regression." (PMID 33261061, 2020). "An additional possibility is that excised tumors of patients could be confronted with ex vivo–expanded autologous NK cells and exogenous cytokines IL-15, IL-18, IL-22, and IL-23 to reactivate the immune response and establish specific tumor recognition." (PMID 33276556, 2020). "Akin to IL-12, IL-18 has been shown to promote anti-tumor responses in several mouse models." (PMID 32708464, 2020). "As expected, IOP also enhanced the secretion of cytokines IL-1β and IL-18 in tumor cells." (PMID 33603669, 2020). "In a TGF-β1-riched milieu such as tumors IL-18 might play a tumor-promoting role decreasing the function of NK cells and reducing the migration of highly cytolytic CD56dim NK cells." (PMID 30641867, 2019). "These opposing effects described for IL-18 in tumorigenesis could be due to the level of IL-18 administered and/or present in the tumor microenvironment." (PMID 31231372, 2019). "This suggests that IL-18 neutralization might be a mechanism by which PCa cells bypass immunesurveillance and promote tumor development." (PMID 30837326, 2019). "However, there is abundant evidence to suggest that in many cancers, IL-18 is more harmful than helpful in regard to tumor angiogenesis and metastasis." (PMID 31293586, 2019). "Additionally, to confirm the differences in IL18 expression in tumor and normal tissues, IL18 expression was analyzed using the GENT database." (PMID 31731729, 2019). "Because NK cells, and recently identified innate lymphoid cells, are well-established tumor-killing cells, many researchers have addressed whether IL-18 therapy rescues cancer expansion." (PMID 30717382, 2019). "Additionally, to identify the associated factors affecting survival rates, we also investigated the correlation between IL-18 expression and the TILs in the tumor environment using the Tumor Immune Estimation Resource (TIMER)." (PMID 31731729, 2019). "In addition to the direct effects of IL-18 on NK cells, the expression of UL16 binding protein 2, which is a ligand for the NK cell-activating receptor, on tumor cells is increased by exogenous IL-18, leading to the increased NK cell cytotoxicity." (PMID 31731729, 2019). "In addition, previous studies suggested that ITGB5 and IL18 are related to tumor invasiveness, whereas CXCL1 and SEMA4F are associated with cell proliferation." (PMID 31118022, 2019). "Collectively, IL-18 might show both anti-cancer and pro-cancer effects depending on tumor environment in the body." (PMID 31731729, 2019). "IL-18 directly enhances NK cell proliferation and migration to secondary lymphoid organs via upregulation of chemokine receptors, allowing them to inhibit the lymphoid spread of tumor cells." (PMID 31731729, 2019).
tumor (continued). "These high levels of IL-18 may play a role in angiogenesis, tumor cell migration, invasion and metastasis." (PMID 31231372, 2019). "In chronic inflammation processes such as those occurring in tumor tissues, IL-18 could support the function of TGF-β1 that is produced/activated by M2-polarized tumor-associated macrophages (TAM)." (PMID 30641867, 2019). "Reasonable explanations for these discrepant and diverse findings may involve three possibilities: the dual impact of IL-18 on tumor-immune responses, the different types of cancer investigated, and variation among the populations under study." (PMID 30925760, 2019). "IFNγ, IL-1β, tumor TNFα, TGFβ, IL-6, and IL-18 are key to the functionality of TAM." (PMID 31430935, 2019). "Moreover, human NK cells from HIV-positive patients have reduced IFNγ production following in vitro IL-12 + IL-18 stimulation and a decreased perforin expression leading to an impaired specific lysis of the K562 tumor cell line." (PMID 31547251, 2019). "The equilibrium between the two opposing roles may rely on the tumor tissue concentration of NO and its relationships with other molecules including IL-18, IFN, and TNF-α." (PMID 31554361, 2019). "In addition, IL-18 can prime NK cells, which potentiate the stimulatory effects of dendritic cells on tumor- specific T-helper cells and cytotoxic lymphocytes in cancer patients." (PMID 29650045, 2018). "Compared with the naïve group and the vehicle group, CTX significantly decreased the thymus and spleen indices, serum hemolysin, NK cell cytotoxicity and serum IL-18 in H22 tumor-bearing mice, suggesting that CTX suppressed the overall immune function of the mice." (PMID 30002398, 2018). "Moreover, tumor-derived IL18 has been demonstrated to increase the immunosuppressive NK cells in which programmed death 1 (PD-1) expression was induced." (PMID 30586414, 2018). "NK cells briefly pre-activated by this combination of cytokines (IL-12, IL-15 and IL-18) were previously shown to have a sustained effector function in tumour mouse models and an enhanced proliferative capacity as well as an increased IFN-γ response over time in human in vitro studies." (PMID 29433450, 2018). "In addition, tumor-derived IL-18 or rIL-18 enhanced B-cell proliferation and IL-10 production in vitro and in vivo." (PMID 29599908, 2018). "Furthermore, compared with the vector control, IL‐18 overexpression promoted tumor cell migration and invasion (P < 0.01), but inhibited growth of tumor cell xenografts (P < 0.05)." (PMID 30524946, 2018). "The major products of inflammasome activation, IL-1β and IL-18, are pro-tumorigenic and shown to play an important role in tumor-mediated angiogenesis, hence blocking their function may suppress tumor progression." (PMID 29558453, 2018). "Also, the use of Salmonella enterica in the bactofection of plasmids encoding interleukin-4 or interleukin-18 induced a systemic increase in IFN-γ and was efficient in delaying tumor growth and prolonging survival in a melanoma murine model." (PMID 30302344, 2018). "However, other studies gave opposite results; namely, IL‐18 was more likely to promote tumor cell EMT." (PMID 30524946, 2018). "Because tumor cell–derived IL-18 and the PD-L1/PD-1 pathway are important in PC cell–induced immune tolerance, targeting these factors may constitute a new immunotherapeutic regimen for PC." (PMID 29599908, 2018). "Studies demonstrated that targeting IL-18 in the tumor microenvironments may improve the efficiency of cancer immunotherapy." (PMID 30211233, 2018). "In particular, compared to the vector control, CRL1623‐IL‐18‐injected tumor xenografts expressed high levels of IL‐18 (P < 0.01), β‐catenin (P = 0.028), TNKS2 (P = 0.045), and N‐cadherin (P = 0.068), but lower levels of E‐cadherin (P = 0.045), and thus the E/N ratio was changed." (PMID 30524946, 2018).
tumor (continued). "The increased tumor number was associated with a colonic upregulation of inflammatory mediators (including Il-1β, Il-6, Tnf, G-csf, Mcp1, and Mip1α, but not Il-18) and an early hyperactivation of mTOR pathway." (PMID 29868004, 2018). "In addition, downregulation of IL-10 and IL-18 by HVT and/or ECpG treatment appears to be linked to defense against MDV infection as demonstrated by the significant reduction of tumor formation and MDV load in feathers." (PMID 30401976, 2018). "IL-18, an IL-1–related cytokine, can be produced by both immune cells and tumor cells." (PMID 29599908, 2018). "However, if IL‐18 has the capacity to promote metastasis in vivo, despite a reduction in tumor size, and the molecular mechanisms by which IL‐18 induces tumor cell EMT in OSCC in vitro need further investigation." (PMID 30524946, 2018). "However, IL18 was also expressed in cancer cells and plays a distinct role in tumor pathophysiology." (PMID 30586414, 2018). "Furthermore, the serum level of IL-18 was also significantly increased in HT29 tumor bearing mice at 6–12 h." (PMID 29690614, 2018). "Treatment with IL-18 promotes regression of melanoma tumor in the NK cell-dependent manner." (PMID 28955340, 2017). "In this study, we investigated the role of tumor derived IL-18 and its effects on NK cells." (PMID 28415798, 2017). "Treatment with NK-activating cytokines, IL-12 and IL-18, or with an IL-2 mutant (H9 “superkine”) increased survival of MHC-I-deficient tumor-bearing mice, accompanied by restoration of effector functions of MHC-I-deficient tumor-infiltrating NK cells." (PMID 28702032, 2017). "Results from hierarchy clustering and linear regression analyses showed that the expression of tumor-associated ASC and IL-18 are closer to ALDH1 expression, NLRP3 and Caspase-1 are close to ALDH1 expression, and NLRP3, Caspase-1, ASC, and IL-18 are close to CD44 and BMI1 expression." (PMID 28865486, 2017). "For instance, tumor cell antigen modulation allows the cells to escape from recognition by T cells and NK cells, thereby downregulating T cell- and NK cell-related immune factors (IL18 and CD300A)." (PMID 28355233, 2017). "To further investigate the molecular mechanism underlying caspase-1-mediated tumoricidal effect, we first tested whether IL-1β and IL-18, two downstream cytokines of caspase-1 (refs 38, 39), contributed to PsV-induced tumour regression." (PMID 28397782, 2017). "Since the antibody treatment did not completely block the cytotoxic activity, other receptors may contribute to the recognition of tumor cells by IL-12/IL-18 activated Vγ9Vδ2 T cells." (PMID 28521284, 2017). "We also examined the effects of IL-18 on the expression of PD-L1 on tumor cells." (PMID 28415798, 2017). "However, IL-18 became incompetent by RNAi interference or the application of IL-18 binding protein (IL-18BP), which activated NK cells to inhibit tumor growth." (PMID 29312552, 2017). "For example, oHSV engineered to express IL-12, IL-18, or IL-4 has improved anti-tumor efficacy." (PMID 26861381, 2016). "However, further studies are needed regarding the unique function of each IL-1 family protein, including IL-1α, IL-1β, and IL-18, in the tumor development." (PMID 27786298, 2016). "Thus, NK cells cultured with IL-15/IL-18 and exposed simultaneously to both drugs were analyzed for their anti-tumor activity and proliferative capability." (PMID 27563819, 2016). "In addition, inhibition of IL-18 signaling during vaccination decreased IFN-γ responses and tumor protection, and that this inhibition suggested stimulatory role of IL-18 in adjuvant effects of α-GalCer and MPL combination." (PMID 26811064, 2016). "However by week 4, E7 DNA vaccine plus α-GalCer and MPL combination mice in the presence of anti-IL-18 mAbs showed an increase in tumor volume over E7 DNA vaccine plus α-GalCer and MPL combination in the presence of isotype control." (PMID 26811064, 2016).
tumor (continued). "IL-18 has been shown to either promote tumor growth or enhance anti-tumor immunity." (PMID 27786298, 2016). "Thus, further investigation into the use of hUMSCs/IL-18 as vehicles of tumor therapy in vivo, including pilot clinical trials, and in combination with other therapies, such as surgery, chemotherapy, endocrine therapy and targeted therapy, is warranted." (PMID 25780408, 2015). "The role of inflammasomes in carcinogenesis is contrasting; they may inhibit tumor promotion by activating caspase-1 and cell killing, or may promote tumor growth by upregulating secretion of pro-inflammatory molecules like, IL-1β, IL-18, FGF2 and HMGB1." (PMID 26689911, 2015). "A previous study evaluated the anti-tumor effects of soluble GM-CSF and IL-18 expressing Lewis lung cancer tumor cells LL/2, the non-specific delivery problem might need to be solved." (PMID 26186692, 2015). "In the intestine, subsets of ILC1 are also cytokine producers (IFN-γ and TNF-α) after in vitro stimulation with IL-12 + IL-15 or IL-12+ IL-18 or after mucosal infection.They can also also degranulate after in vitro stimulation in the presence of tumor cell line." (PMID 26630176, 2015). "Inactivation of the apoptotic pathway is one of the features of tumor cells, and it may also be one of the important mechanisms of the antitumor effect of IL-18." (PMID 25591548, 2015). "Taken together, these results indicated that IL-18 might be a good candidate as an adjuvant to enhance the tumor protective effects of GM-CSF." (PMID 26186692, 2015). "In this study we demonstrated that membrane-bound IL-18 may increase anti-tumor effects used in combination with GM-CSF." (PMID 26186692, 2015). "Importantly, CT26/GM-CSF/IL-18 reduced tumor growth significantly in comparison with CT26/GM-CSF (P<0.05)." (PMID 26186692, 2015). "Since tumor cells secrete IL-18 that upregulates PD-1 on NK cells, anti-IL-18 neutralizing mAb in combination with Nivolumimab may circumvent tolerization of NK cells." (PMID 25972872, 2015). "Moreover, mRNA levels of inflammatory cytokines such as IL1β, IL6 and IL18 were found to be augmented in the tumor tissue after LTX-315 treatment." (PMID 26472184, 2015). "As IL-12 and IL-18 have an important role in improving anti-tumor immune response they could have a great potential in cancer immunotherapy." (PMID 25889680, 2015). "IL-18 secretion by tumor cells upregulates PD-1 on NK cells." (PMID 26779186, 2015). "A 2007 study adopted a new approach by establishing a prognostic correlation between HCC tumor stage and aggressiveness and interleukin 18 (IL-18), which is speculated to be part of an antitumor response by adjacent healthy hepatocytes." (PMID 25866565, 2015). "In the IL-18 and TK/GCV combination gene therapy group, infiltration of CD4+ T cells at the injection site of IL18-TK52 cells indicated that the local pre-treatment of IL-18 might maintain the T-lymphocyte status around the tumor." (PMID 25051201, 2014). "IL-18, however, seems to play a tumor-suppressive role in CAC." (PMID 24474192, 2014). "Utilizing different murine tumor models, we have previously reported that systemic levels of IL-12 alone or together with IL-18, induced after hydrodynamic injection of the respective cDNAs, completely abrogated subcutaneous tumor growth and pulmonary and hepatic metastases." (PMID 24587231, 2014). "Furthermore, they reported that NLRP3-inflammasome activation in hematopoietic cells is critical for the tumor suppressive function, which has been attributed to IL-18 production." (PMID 24474192, 2014). "Furthermore, it was demonstrated that IL-18 derived from tumor cells had the ability to subvert the NK cell-mediated tumor immunosurveillance and to promote tumor progression in a programed death receptor 1 (PD1)-dependent manner." (PMID 25071785, 2014). "This may be related with an IL-28-mediated increase in the expression of VEGF-C and IL-18 in tumor cells." (PMID 25075523, 2014).
tumor (continued). "Same as the neutrophils from naive mice, the tumor-promoting neutrophils could produce more IL-18, and express higher levels of NK-activating ligands RAE-1, MULT-1, and H60 after priming by IFN-γ and TNF-α." (PMID 25587026, 2014). "In conclusion, IL-18 is a novel cytokine with potent dual effects on tumor progression." (PMID 24963217, 2014). "Indeed IL-18 has been shown to promote tumor immuno-suppression and tumor growth by converting Kit− NK cells into Kit+ NK cells." (PMID 24376448, 2013). "Cytokines generated by neutrophils, such as vascular endothelial growth factor, interleukin-18 and matrix metalloproteinases, may establish a microenvironment that promotes angiogenesis, and thus promotes tumor growth and metastasis." (PMID 23705622, 2013). "The increased tumor burden correlates with attenuated levels of IL-1β and IL-18 at the tumor site." (PMID 23847622, 2013). "Interestingly, we observed EGF-induced alternative promoter usage of genes that have previously been implicated in tumor progression (e.g., VEGFC, PTK2, IL18 and VAV3) or in cell survival/proliferation (e.g., FBXW7, BID, ABL2)." (PMID 24324612, 2013). "To clarify whether M.hy promoted tumor development via inflammasome activation, we analyzed monocytes for IL-1β and IL-18 production upon M.hy challenge." (PMID 24223129, 2013). "IL-18 also promotes metastasis by inducing cell adhesion molecules and MMPs, while facilitating immune evasion by increasing the expression of Fas ligand on tumor cells." (PMID 23847622, 2013). "In contrast, IL-18 has been implicated in promoting tumor metastasis from the lung, but in a T-cell and B-cell independent fashion; tumor-derived IL-18 promoted increased expression of the inhibitory receptor PD-1 on NK cells and prevented effective immunosurveillance." (PMID 24409181, 2013). "Blockade of tumor-derived IL-18 markedly prevented NKreg accumulation and melanoma dissemination." (PMID 23269924, 2012). "Furthermore, in both RAG1−/− and immunologically intact mice, IL-18 correlated with greater tumor infiltration of macrophages and neutrophils." (PMID 21935389, 2011). "In addition, although the tumor draining lymph nodes of IL-18-treated mice had fewer CD4+ T cells, CD8+ T cells and NK cells per lymph node, they represented a higher percentage of lymph node cellularity than those of the αIL-18 group." (PMID 21935389, 2011). "Furthermore, direct injection of IL-18 into tumors, a clinically relevant means of administration, also inhibited tumor growth." (PMID 21935389, 2011). "Other studies have also shown that intratumoral injection of IL-18 can inhibit tumor growth." (PMID 21935389, 2011). "In this study however we sought to mainly explore the ability of those drugs to render tumor cells more susceptible to immunotherapy with IL-18, and specifically focused on effector mechanisms, and not the drugs' overall effects on the immune system." (PMID 21609494, 2011). "IL-18 has anti-tumor effects in several murine models of cancer." (PMID 21935389, 2011). "IL-18 treatment resulted in complete tumor regression in 3 of 10 mice." (PMID 21935389, 2011). "Our results also suggest a role for innate immunity in IL-18-induced tumor suppression." (PMID 21935389, 2011). "This indicates that IL-18 is far more effective at the tumor site in generating anti-tumor effects." (PMID 21935389, 2011). "Furthermore, direct injection of IL-18 into tumors, a clinically relevant means of administration, also inhibited tumour growth." (PMID 21935389, 2011). "Since IFN-γ is an effector molecule downstream of IL-18 with important functions in Th1-responses, we hypothesized it may mediate the anti-tumor effects of IL-18." (PMID 21935389, 2011). "Therefore, RVL inhibited IL-18 secretion from tumor-activated HSE cells through the specific inhibition of tumor-derived VEGF on HSE." (PMID 21569399, 2011).